BRCA1 (BRCA1 DNA repair associated)
Diseases named in the same sentence as BRCA1 in open-access papers (continued):
Sharing a sentence is not in itself a finding about the gene and the disease.
tumor (continued). "In this work we have studied the effect that VRK1 depletion has on the cellular response to olaparib, a drug which is currently used to sensitize tumor cell to ionizing radiation, and facilitates tumor elimination in cells with altered DNA repair pathways, such as those with BRCA1 or ATM mutations." (PMID 31101118, 2019). "For this reason we were able to identify two additional tumor cases with mutations in other DNA damage response genes than BRCA1/2 (PALB2 and NBN), which might also respond to PARP-inhibitor therapy." (PMID 31029168, 2019). "Hence, the introduction of a diagnostic test able to identify both germline and somatic BRCA1/2 alterations in tumor specimens has become necessary to guide treatment choice, even right after the surgery." (PMID 31653094, 2019). "We speculate that this would also apply to other tumor types in which BRCA1 mutations are found such as ovarian and pancreas." (PMID 30993195, 2019). "A third tumor from a BRCA1 phenocopy had a BRCA1 Q309R deleterious variant (Polyphen score .999)." (PMID 31346352, 2019). "Singh (2015) observed a strong significant association of mutation of BRCA1 gene and the age at diagnosis in the North Indian women, BRCA1 mutation was more frequently observed in tumor sample obtained from women who were ≤ 40 years of age (11.9%) than those >40 years old (1.2%)." (PMID 31759379, 2019). "Aside from enrichment of breakpoints in genes and exons, we also wanted to test whether there are larger regions of the genome, including non-coding regions, that are enriched for indel or SV breakpoints in our set of 46 BRCA1/2-mutated tumor samples." (PMID 31182087, 2019). "We found that several serum tumor markers were associated with BRCA1/2 mutation status." (PMID 30972954, 2019). "This may indicate that loss of BRCA1 leads to tumor cells undergoing replication stress with inefficient DNA." (PMID 31295843, 2019). "Furthermore, we found that the BRCA1-reconstituted tumor cells were more sensitive than the BRCA1-mutated cells to histone deacetylase (HDAC) inhibitor-induced differentiation." (PMID 31273285, 2019). "Similar lesions are induced by DNA‐alkylating agents, which include mono‐functional (e.g. mitomycin C, nimustine) or bifunctional alkylators (e.g. chlorambucil, cyclophosphamide, melphalan), some showing specific toxicity against BRCA1/2‐deficient cells and tumours." (PMID 31273933, 2019). "Most importantly, the binding with the E2 ubiquitin-conjugating enzyme UbcH5a (MIM# 602961) enables the BRCA1-BARD1 complex to acquire an ubiquitin ligase activity, linked to BRCA1 tumor suppression function by regulating transcription and double stand break (DSB) repair." (PMID 30696104, 2019). "Given the relatively low number of observed tumours carrying mutations in BRCA1/2 genes, some of the statistical analyses performed through the paper may benefit from future assessments on larger cohorts." (PMID 31182087, 2019). "This is in line with the hypothesis of LOH (loss of the corresponding BRCA1/2 wild type allele) having occurred in all tumors that were analyzed, especially considering a tumor content of about 70–80% was determined." (PMID 31029168, 2019). "Thus, there is a clear necessity for identifying new drugs or drug combinations that can target BRCA1/2‐deficient cells and tumours." (PMID 31273933, 2019). "BRCA1 is a tumor suppressor and its methylation has been associated with loss of BRCA1 expression." (PMID 31533668, 2019). "However, the absolute increase in the CSC-like population in the BRCA1-reconstituted tumor cells under hypoxia remains small as compared to that in the BRCA1-mutated parental cells." (PMID 31273285, 2019). "Structural variants may play an important role in characterizing BRCA1/2-mutated tumours and we advocate that future efforts in this direction may shed light on the unique features of these tumours." (PMID 31182087, 2019).
tumor (continued). "Because BARD1 may interact with other molecules implicated in genome integrity, a BRCA1-independent tumor suppressor functions for BARD1 have also been suggested." (PMID 31142030, 2019). "In order to assess whether a complete loss of BRCA1 underpinned tumor development in patient 1 and explained the BRCA1 promoter methylation above 0.50 detected in the tumor tissue, the loss of heterozygosity (LOH) at chromosome 17 was investigated." (PMID 30634417, 2019). "Overall, 9 in 11 patients with HBOC‐related tumor had BRCA1/2 deleterious mutations." (PMID 30972954, 2019). "Initially, it was found that PARP inhibitor (PARPi) could effectively kill BRCA1/2 mutated tumor cells." (PMID 31737426, 2019). "BARD1 may act as a tumor suppressor in the BRCA1-dependent pathways, which is associated with specific BRCA1/BARD1 heterodimer formation via N-terminal RING-finger domains." (PMID 31142030, 2019). "Whether and how estrogen activates EMT in BRCA1-deficient, ER-negative basal-like tumor cells to promote their tumor initiation and progression remain elusive." (PMID 29996906, 2018). "Together, these results demonstrate that in addition to the increased tumor-initiating potential of ER-positive Brca1-proficient tumor cells, estrogen enhances the number of Brca1-deficient CSCs and promotes ER-negative basal-like tumor initiation and progression." (PMID 29996906, 2018). "In this study, we found that deletion of Brca1 enhances the tumor-initiating potential of tumor cells, and that estrogen stimulates proliferation and the tumor-initiating potential of both Brca1-proficient ER-positive and Brca1-deficient ER-negative tumor cells." (PMID 29996906, 2018). "To address whether DNA repair genes may have a role in BRCA1 tumorigenesis, we performed a sequence analysis in tumor samples from HBOC patients carrying BRCA1wt, BRCA1 mutations, or BRCA1 missense variants." (PMID 30283497, 2018). "Whether estrogen promotes EMT and proliferation of ER-negative BRCA1-deficient tumor cells through activation of the PI3K/AKT pathway remains elusive." (PMID 29996906, 2018). "In summary, our results indicate that alterations in gene methylation profiles are common in MBC and that tumor-associated gene methylation patterns may identify specific MBC subgroups related to BRCA1/2 mutation status and clinical-pathologic characteristics." (PMID 29731982, 2018). "We next tested whether overexpression of cyclin B1 attenuates the survival of BRCA1-associated tumor cells." (PMID 30327455, 2018). "Instead, she recommended providing a brochure that summarizes the key points and after explaining these points in simple terms, spending more time considering and addressing the patient’s actual worries (e.g., talking about the risk to daughters instead of BRCA1 being a tumor suppressor)." (PMID 30227649, 2018). "Based on these data, we were particularly interested in ZNF350 encoding zinc finger protein 350 (ZNF350/ZBRK1) that has been suggested to function as a tumor suppressor, namely repression of metastasis/invasion, via interaction with breast cancer 1 (BRCA1) and KRAB-ZFP-associated protein 1 (KAP1)." (PMID 30613364, 2018). "In the ARIEL2 and ARIEL3 clinical trials, although BRCA mutations or genomic LOH was associated with better tumor response than BRCA1 or RAD51C methylation, copy number profile or mutations in other relevant genes, the outcome with rucaparib was generally better than that obtained with placebo." (PMID 30518089, 2018). "As well-known, chemotherapy alters pathways involved in DNA damage repair; for this reason, PARP inhibitors can sensitize tumor cells to chemotherapy and radiotherapy and can induce synthetic lethality in tumors from patients with hereditary or sporadic mutations in BRCA1/2 genes." (PMID 30234015, 2018). "Consequently, BRCA1 deficiency has possibly a key role in breast malignancy process, apart from tumor subtypes." (PMID 28646826, 2018).
tumor (continued). "In this respect, adopting prophylactic strategies for carriers of a germline mutation in the BRCA1/2 genes could reduce costs and need for palliation in cases of tumor progression." (PMID 30517521, 2018). "In addition, in a cohort of 560 individuals with BC, HRDetect identified 22 tumours with somatic loss-of-BRCA1 or BRCA2 and 47 tumours with functional BRCA1/2 deficiency, none of which had mutations detected with standard analysis." (PMID 29867226, 2018). "We verified the same pathogenic (class 5) BRCA1 mutation in different tumor locations." (PMID 29855275, 2018). "Host estrogen in recipient mice may play a role in ER-negative BRCA1-deficient tumor growth and progression." (PMID 29996906, 2018). "This is more technically challenging than germline testing, but does have the advantage that germline and somatic variants can be identified in a single sample taking the combined tumor BRCA1/2 mutation frequency to almost a third of high grade serous ovarian cancers." (PMID 29215764, 2018). "Furthermore, the development of resistance to cisplatin or PARPi involves restoration of BRCA1/2 function, achieved either by the second mutation in the affected copy of the gene or selection of pre-existing BRCA1-proficient tumor cells." (PMID 30211169, 2018). "Taking into consideration our finding that estrogen promotes EMT, proliferation, sphere-forming potential, and Akt activation in Brca1-deficient tumor cells in vitro, these results suggest that host estrogen likely promotes Brca1-deficient tumor initiation, which support our conclusion." (PMID 29996906, 2018). "Immuno-histochemical staining of the tumor could confirm the reduced expression of BRCA1 protein for the variant carriers." (PMID 30453575, 2018). "BRCA1/2 heterozygosity also contributes to some instances of pancreatic, prostate and gastric cancers, although these associations are described in a less systematic way as compared to the neoplasms of female reproductive tract." (PMID 30211169, 2018). "Disruption of this complex due to BRCA1 protein dysfunction resulting from either BRCA1 gene mutation or epigenetic silencing, may have huge implications for tumour cell anabolism." (PMID 30323899, 2018). "Genomic instability caused by BRCA1/2 gene inactivation may also result in tumor responsiveness to immune therapy." (PMID 30211169, 2018). "BRCA1 deficiency can lead to defects in the S phase, G2/M phase, and spindle checkpoints, causing genetic instability and thus triggering DNA damage response, further increasing the risk of tumor formation." (PMID 29492227, 2018). "In addition, knockdown of oncomir miR-155 in BRCA1-deficient cells significantly inhibits in vivo tumor growth." (PMID 30558184, 2018). "A consensus panel of such molecular alterations could serve as biomarker for monitoring the risk of developing neoplastic disease in these patients as do BRCA1, BRCA2 and ER/PR/HER2 biomarkers for BCa25–27,52." (PMID 30054559, 2018). "Next generation sequencing-based assays that detect putative markers of HRD in tumour tissue or ctDNA, beyond, BRCA1/2 mutational status, may have potential as predictive biomarkers in certain clinical settings but further research is required." (PMID 29464354, 2018). "Thus, PARP inhibitors selectively kill tumour cells with disordered expression of BRCA1/2 (mutation or loss)." (PMID 28800752, 2017). "CX-5461 is now in advanced phase I clinical trial for patients with BRCA1/2 deficient tumours (Canadian trial, NCT02719977, opened May 2016)." (PMID 28211448, 2017). "Besides having a tumor profile characteristic of tumors with a poor prognosis, the family history associated with those carrying a pathogenic BRCA1 mutation was more severe than the WT or with a VUS, as it would be expected." (PMID 27926510, 2017). "First, BRCA1-IRIS overexpression was associated with smaller tumor size." (PMID 28499366, 2017).
tumor (continued). "We combined cellular models for BRCA1/2 inactivation with xenograft tumor growth in mice to demonstrate that exogenous acetaldehyde effectively and selectively reduced the survival of BRCA1/2‐deficient cells and tumors including those that are PARP inhibitor‐resistant." (PMID 28729482, 2017). "Thus, reduced tumour incidence in DKO mice is unlikely due to rescue of either HR repair defect or elevated DNA replication stress associated with BRCA1 deficiency." (PMID 28649985, 2017). "In patients whose tumor exhibit HR deficiency, e.g., through BRCA1/2 mutations, double-stranded DNA (dsDNA) repair is impaired, leading to cells becoming increasingly reliant on PARP as a primary mechanism of DDR and in turn, making them exquisitely sensitive to PARP inhibition." (PMID 28829366, 2017). "These tumours are histologically and molecularly similar to BRCA1-associated breast tumours." (PMID 29259228, 2017). "Importantly, acetaldehyde specifically inhibits in vivo the growth of BRCA1/2‐deficient tumors and ex vivo in patient‐derived tumor xenograft cells (PDTCs), including those that are resistant to poly (ADP‐ribose) polymerase (PARP) inhibitors." (PMID 28729482, 2017). "However, studies involving methylation analysis in tumor tissue of patients carriers of a BRCA1 germline pathogenic mutation are scarce." (PMID 27926510, 2017). "Interestingly, this profile was associated with either inactivation of BRCA1 in the tumor via mutation or promoter hypermethylation, or via inherited germline variants." (PMID 28606096, 2017). "In this analysis of Study 19, we have distinguished somatic from germline BRCA1/2 mutations by tumor sequencing and analysis in order to test the hypothesis that somatic BRCA1/2 mutations should have similar functional effects to germline mutations." (PMID 28525389, 2017). "Basal A cell lines are associated with the up-regulation of several genes in the E-twenty-six transformation-specific (ETS)-pathway and mutations of the tumor suppressor genes BRCA1 and 2; while the basal B cell lines are Claudin-low and display mesenchymal and stem cell-like characteristics." (PMID 29348886, 2017). "FANCJ, originally designated BRCA1-interacting C-terminal helicase 1 (BACH1) (or BRCA1-interacting protein 1 (BRIP1)) for its interaction with the tumor suppressor BRCA1, is genetically implicated in the progressive bone marrow failure disorder Fanconi Anemia (FA)." (PMID 28594346, 2017). "Although this association might indicate an influence of BRCA1 cytoplasmic retention on tumor progression, the mechanism and direction of causality in this association are uncertain." (PMID 28863181, 2017). "In addition, reports on the association of BRCA1 promoter methylation with the hormone receptor status of the tumor are inconsistent." (PMID 28403857, 2017). "We next analyzed whether RANK expression was already present in the earliest tumor lesions detectable in the breast tissue of BRCA1 mutation carriers." (PMID 27241552, 2016). "Therefore, PARG depletion cannot be considered as a strategy to kill tumour cells mutated in BRCA1 or PTEN." (PMID 27375368, 2016). "Among tumours with data on stage and grade, the majority of BRCA2 mutation carriers presented with stage 2 disease (47 %) and tumours of histologic grade 3 (56.7 %), whereas the majority of BRCA1 mutation carriers presented with stage 3–4 disease (42.9 %) and histologic grade 3 tumours (69.2 %)." (PMID 26857456, 2016). "Additionally, it is related to the basal-like group obtained via genetic analysis and to tumours associated with changes in the BRCA1 gene." (PMID 27170832, 2016). "Nonetheless the same group reported that annual mammography screening beyond 60 years of age in BRCA1/2 carriers is associated with a marked improvement in tumour stage at diagnosis, with 58 % diagnosed at stage two or above with usual two-yearly screening compared to only 21 % in the annual group." (PMID 27087880, 2016).
tumor (continued). "Interestingly, review of the NGS data for this case demonstrated that this tumor had a single copy deletion of the BRCA1 gene, suggesting that BRCA1 loss was likely due to single copy deletion of BRCA1 and epigenetic silencing of the complementary allele." (PMID 26871470, 2016). "This provides means for selective targeting of BRCA1/2‐mutated cells and tumours." (PMID 27037238, 2016). "Considering the oncogenic role of miR-155 and its up-regulation in BRCA1-deficient tumors we reasoned its inactivation might increase the tumor latency or reduce the tumor incidence." (PMID 26848978, 2016). "These types of tumours are associated with BRCA1 and BRCA2 mutations." (PMID 27884978, 2016). "Considering our current findings, abrogation of Plk1 phosphorylation site in this BRCA1 variant could very likely participate in the disruption of BRCA1 function in the tumor." (PMID 26745677, 2016). "Furthermore, downregulated genes were enriched in DNA damage response pathways, thereby supporting the growing evidence for BRCA1 haploinsufficiency in DNA damage repair as a potential early tumor predisposing event." (PMID 27534398, 2016). "Moreover, the use of tumor tissue for mutational analysis allowed the detection of both somatic and germline BRCA1/2 mutations." (PMID 27167707, 2016). "In this regard, our present results established that pharmacological ablation of BRCA1 mutation-driven hyperactivation of mitochondrial-dependent biosynthetic activity was sufficient to reduce the tumor-initiating capacity of breast epithelial BRCA1 one-hit cells in mammosphere assays." (PMID 27259235, 2016). "The finding that MBCs associated with BRCA1 mutations are frequently ER+ suggests that the hormonal milieu may be a mechanism controlling ER status in BRCA1 tumours." (PMID 26857456, 2016). "Interestingly, the polyadenylation factor CstF associated to the tumor suppressors BRCA1/BARD1 play a role in the proteasome-mediated degradation of POLR2A during DDR." (PMID 27462460, 2016). "BRCA1 is expressed in breast and other tissues, where it helps to repair damaged DNA by forming a large multiprotein complex known as the BRCA1-associated genome surveillance complex with DNA damage sensors and other tumor suppressors." (PMID 26885691, 2016). "Therefore, PARG depletion cannot be considered as a strategy to kill tumours cells mutated in BRCA1 or PTEN." (PMID 27375368, 2016). "Thus, BRCA1 became a central tumor predisposition gene and its biology has been a subject of intense investigations." (PMID 27027444, 2016). "At present, a variety of selection criteria are used to determine the eligibility for BRCA1/2 testing, including family history, age at onset, tumor clinicopathological features, and computational risk prediction models (BRCAPRO, BOADICEA, Myriad, and Manchester scoring system)." (PMID 27242959, 2016). "However, in recent years it has become possible to exploit the DNA-repair defects in tumours carrying BRCA1 or BRCA2 gene mutations using PARP inhibitors." (PMID 27463681, 2016). "If confirmed in human cells, this assay could define subcategories in the pathogenic variants of BRCA1, based on different cellular mechanisms leading to tumor development." (PMID 27272900, 2016). "However, the loss of one half of the protective dosage of BRCA1/2 proteins increases the risk of tumor formation preferentially in hormone-dependent tissues such as mammary and ovarian epithelia." (PMID 26943589, 2016). "This raises the question, how can tumor cells survive with loss of both BRCA1 alleles?" (PMID 26943589, 2016). "Although the data are scarce, our review supports what was earlier suggested by others, i.e. that that the therapy response of tumours in BRCA1/2 mutation carriers might be better compared to that in non-carriers." (PMID 25816289, 2015). "Alterations in the HR pathway different from BRCA1/2 mutations may determine an HR-deficient phenotype similar to BRCA-deficient tumor (namely, BRCAness)." (PMID 26268938, 2015).